TOMM40L (translocase of outer mitochondrial membrane 40 like)
Description:
Potential channel-forming protein implicated in import of protein precursors into mitochondria.
Synonyms: TOMM40B; FLJ12770
Tractability: PROTAC: ubiquitination databases record sites on it; its protein half-life has been measured.
Safety:
Unwanted effects reported when the protein is acted on. In parentheses: how it was acted on, where the effect was seen, and who reports it.
anemia (source: ClinPGx)
Gene: Protein-coding gene on chromosome 1 (161,225,939 to 161,233,754, forward strand). Ensembl gene ENSG00000158882.
Subcellular location: Mitochondrion outer membrane
Gene Ontology:
Molecular function: protein transmembrane transporter activity
Biological process: protein import into mitochondrial matrix; transmembrane transport
Cellular component: mitochondrion; protein-containing complex; mitochondrial outer membrane translocase complex; mitochondrial outer membrane
Genetic constraint (gnomAD): Loss-of-function variants: 17 observed, 40.19 expected, observed/expected ratio (o/e) 0.42, 90% interval 0.29 to 0.63. The upper end of that interval is the gene's LOEUF score, 0.63, which puts it in group 2 of 6, group 1 being the genes least tolerant of losing a copy. Missense variants: 294 observed, 409.24 expected, observed/expected ratio (o/e) 0.72, 90% interval 0.65 to 0.79. Synonymous variants: 151 observed, 158.97 expected, observed/expected ratio (o/e) 0.95, 90% interval 0.83 to 1.09.
Homologues: Orthologues: chimpanzee TOMM40L (100% identical), macaque TOMM40L (99% identical), dog TOMM40L (99% identical), pig TOMM40L (99% identical), rabbit TOMM40L (98% identical), mouse Tomm40l (98% identical), rat Tomm40l (97% identical), guinea pig TOMM40L (91% identical), tropical clawed frog tomm40l (70% identical), Drosophila melanogaster tomboy40 (44% identical), Drosophila melanogaster Tom40 (43% identical), Caenorhabditis elegans tomm-40 (39% identical). Paralogues in human: TOMM40 (62% identical).
Diseases named in the same sentence as TOMM40L in open-access papers:
TOMM40L is named in the same sentence as 9 diseases in open-access papers, as found by Europe PMC text mining. Sharing a sentence is not in itself a finding about the gene and the disease. The quoted sentences say what the papers report.
pancreatic cancer (2 papers, 2020 to 2025). "The expression level of TOMM40L gene was upregulated in gemcitabine-resistant pancreatic cancer cell lines in a time-dependent manner, thus showing its potential as a candidate biomarker for diagnosis and treatment." (PMID 40746880, 2025). "Similarly, TOMM40L is downregulated in gemcitabine-resistant pancreatic cancer cells compared with their parental sensitive counterparts." (PMID 32260415, 2020).
Alzheimer disease (1 paper, 2022). A progressive, neurodegenerative disease characterized by loss of function and death of nerve cells in several areas of the brain leading to loss of cognitive function such as memory and language. "Although polymorphisms encoding TOMM40 have been shown to be associated with an increased risk of late-onset Alzheimer’s disease, further studies are needed to elucidate the function and mechanism of TOMM40L in the future." (PMID 36544763, 2022).
epithelial ovarian cancer (1 paper, 2020). "TOMM40L, also upregulated in our study, is upregulated in epithelial ovarian cancer cell lines overexpressing DOK1, a candidate tumor suppressor associated with cisplatin sensitivity." (PMID 32260415, 2020).
hepatocellular carcinoma (1 paper, 2023). A malignant tumor that arises from hepatocytes. "The qRT-PCR results showed that TOMM40L, SNRPA, ILF3, CPSF6, and NUP205 were remarkably highly expressed in hepatocellular carcinoma." (PMID 37745063, 2023).
liver cancer (1 paper, 2025). An epithelial or non-epithelial malignant neoplasm that arises from the liver. "Male patients had higher TOMM40L protein levels than female patients, suggesting worse prognosis for males, consistent with studies indicating higher recurrence risk post-surgery in male liver cancer patients." (PMID 40746880, 2025).
Parkinson disease (1 paper, 2013). A progressive degenerative disorder of the central nervous system characterized by loss of dopamine producing neurons in the substantia nigra and the presence of Lewy bodies in the substantia nigra and locus coeruleus. "Our results showing molecular mimicry between TMV and human TOMM40L raise the question as to whether TMV has a potential role in smokers against Parkinson’s disease development." (PMID 23573274, 2013).
cancer (3 papers, 2017 to 2025). A tumor composed of atypical neoplastic, often pleomorphic cells that invade other tissues. "Among other genes that were clustered with STS were several genes with ubiquitous expression in the normal tissues and documented overexpression in cancers: SLC26A6, TOMM40L, AKR1B1, NDRG2 and DGAT1 (based on TCGA data)." (PMID 29088719, 2017). "Similarly, TOMM40L, a component of the TOM complex, likely supports cancer progression by enhancing mitochondrial function, akin to TOMM20's role in promoting cell proliferation, migration, and invasion in cancer." (PMID 39744494, 2025).
tumor (2 papers, 2020 to 2025). "Further, we associated the SRS with the tumor microenvironment and drug sensitivity, identifying and validating the oncogenic role of key gene TOMM40L, providing new perspectives for HCC diagnosis, treatment, and prognosis." (PMID 40746880, 2025). "We found that the levels of TOMM40L in tumor tissues were significantly increased at both the mRNA and protein levels." (PMID 40746880, 2025). "After categorizing 76 HCC cases into groups based on TOMM40L protein levels in tumor tissues, a low expression group and a high expression group were established." (PMID 40746880, 2025). "Bioinformatics analysis evaluated tumor immune infiltration characteristics and drug sensitivity in different SRS subgroups, identifying the key gene TOMM40L." (PMID 40746880, 2025). "Furthermore, significant upregulation of key SRGs like TOMM40L in HCC, in contrast to adjacent non-tumor tissues, was observed." (PMID 40746880, 2025).
TOMM40L also shares sentences with these, for which no sentence is quoted: asthma (1 paper).